IL6 (interleukin 6)
Diseases named in the same sentence as IL6 in open-access papers (continued):
Sharing a sentence is not in itself a finding about the gene and the disease.
rheumatoid arthritis (continued). "IL-6 blockade is an effective therapy for rheumatoid arthritis in clinical practice, although some patients fail to respond to treatment." (PMID 31699146, 2019). "IL‐6 also increases VEGF expression in human umbilical vein endothelial cells in a model studying angiogenesis in rheumatoid arthritis." (PMID 31016754, 2019). "HS exerted treatment effects on RA by regulating 4 core targets (CSF2, IL1β, TNF, and IL6), which involved in 15 pathways such as rheumatoid arthritis, TNF signaling pathway, and cytokine-cytokine receptor interaction." (PMID 31885670, 2019). "IL-6, a cytokine involved in the pathogenesis of various chronic inflammatory diseases, including crohn’s disease, rheumatoid arthritis, asthma, and lupus." (PMID 31249603, 2019). "IL-6 is a pro-inflammatory cytokine that plays an important role in inflammatory diseases such as rheumatoid arthritis, systemic juvenile arthritis, psoriasis, and ankylosing spondylitis." (PMID 30567287, 2018). "miR-451 inhibits inflammatory cytokines secretion of TNF-α, IL-1β, and IL6 in human rheumatoid arthritis." (PMID 29652844, 2018). "Tocilizumab, an anti-interleukin-6 (IL-6) agent, is indicated as a treatment for several autoimmune or inflammatory diseases, including rheumatoid arthritis (RA) and juvenile idiopathic arthritis (JIA)." (PMID 30547812, 2018). "During rheumatoid arthritis (RA), high levels of IL-6, IL1β and GM-CSF were described in the inflamed joints." (PMID 30074983, 2018). "IL-6, is tied to excessive promotion of RANKL and inhibition of OPG and thus has been linked to bone osteolysis, osteoporosis, rheumatoid arthritis and other bone-related pathologies." (PMID 30671025, 2018). "In rheumatoid arthritis, IL-6 has the function of increasing the effect and secretion of IL-1 and TNF-α and is also the main marker that is associated with disease activity." (PMID 29805310, 2018). "Psoriasis, PsA and rheumatoid arthritis are characterised by the secretion of several pro-inflammatory cytokines such as IL-2, IL-6, IL-8, IFN-γ and TNF-α." (PMID 29587639, 2018). "In rheumatoid arthritis (RA), adipokines contribute to the inflammation process in the joint by inducing the expression of pro-inflammatory cytokines such as IL-6, IL-8, and MMP-1 in synovial fibroblasts and other synovial cells." (PMID 30208657, 2018). "In inflammatory disorders such as rheumatoid arthritis, IL-6 has been shown to enhance the formation and activity of osteoclasts and inhibit the formation and activity of osteoblasts." (PMID 29423066, 2018). "SSB intake was also associated with IL-6 and TNF-α, and recent studies link SSB intake to the inflammatory disease rheumatoid arthritis." (PMID 29757229, 2018). "The TWEAK/Fn14 interaction is particularly important in synovial inflammation associated with rheumatoid arthritis (RA); higher serum levels of TWEAK, TNF-α, and IL-6 have been reported in RA patients as compared to normal controls." (PMID 30576385, 2018). "Multiple proinflammatory cytokines, such as IL-1β, IL-6, TNF-α, and IL-17, cause cartilage damage and bone destruction in aggravation of rheumatoid arthritis." (PMID 29751535, 2018). "Tocilizumab, an anti-interleukin-6 (IL-6) agent, is indicated as a treatment for several autoimmune or inflammatory diseases, including rheumatoid arthritis and juvenile idiopathic arthritis (JIA)." (PMID 30547812, 2018). "Clinical trials for tocilizumab, a blocking antibody for the IL-6 receptor, revealed decreased IL-6 levels, improved disease activity scores, and symptoms in rheumatoid arthritis." (PMID 30380761, 2018). "Another observational study conducted in rheumatoid arthritis patients has found that serum vitamin D levels were negatively correlated with the levels of IL‐6 and TNF‐a." (PMID 29484258, 2018). "The levels of IL-6 and its receptor are elevated in synovial fluid and serum in humans with rheumatoid arthritis." (PMID 29867478, 2018).
rheumatoid arthritis (continued). "In an in vitro co-culture system, we show that Rev-erb agonist can suppress macrophage transcript levels of select inflammatory genes (IL6, TNFα, CCL2, and MMP9), which are involved in rheumatoid arthritis and implicated in alphavirus-induced joint pathology." (PMID 30568983, 2018). "Dysregulation or overproduction of IL-6 leads to autoimmune diseases such as multiple sclerosis (MS) and rheumatoid arthritis (RA), in which Th17 cells are considered to be the primary cause of pathology." (PMID 29853890, 2018). "Interleukin-6 (IL-6) is involved in the pathogenesis of various inflammatory diseases, like rheumatoid arthritis (RA)." (PMID 30597965, 2018). "Numerous bone diseases are tied to IL-6 overexpression, including rheumatoid arthritis, osteoporosis, and bone-metastatic cancers." (PMID 30671025, 2018). "Anti-IL-6 therapy has been proven to be clinically efficacious in treating rheumatoid arthritis and has been studied for treatment of graft versus host disease, among other applications." (PMID 29410442, 2018). "Tocilizumab, anti-inflammatory drug, is a humanised monoclonal antibody that inhibits IL-6 signalling and is licensed in the UK for treatment of rheumatoid arthritis." (PMID 30244217, 2018). "Blocking antibodies to IL-6 and its receptor have been studied in other inflammatory diseases, such as rheumatoid arthritis and Crohn’s disease." (PMID 30380761, 2018). "In a study in patients with rheumatoid arthritis, IL-6 concentrations decreased during 6 months in the minocycline treatment group but not in the placebo group." (PMID 30322824, 2018). "Inhibition of IL-6 via antibodies against IL-6 (siltuximab) or IL-6R (tocilizumab, sarilumab) is a proven therapeutic strategy in inflammatory diseases, such as rheumatoid arthritis, and is under investigation in cancer." (PMID 30279971, 2018). "IL-6 level was elevated in numerous inflammatory diseases such as rheumatoid arthritis, systemic lupus erythematosus and psoriasis, suggesting its close involvement in inflammation." (PMID 30104977, 2018). "Recently, anti-IL6 directed therapies have been used clinically to treat various diseases, such as rheumatoid arthritis." (PMID 28186964, 2017). "Clinical data also demonstrate the improvement of rheumatoid arthritis by IL-6R blockade despite increased blood IL-6 levels after the administration of MR16-1." (PMID 29078808, 2017). "Platelet MVs aggravate LPS-induced damage of pulmonary endothelial cells, increase the adhesion of monocytes to endothelial cells, and induce IL-6 and IL-8 in an IL-1β dependent fashion in synovial joints of rheumatoid arthritis (RA) patients." (PMID 28491866, 2017). "Only two drugs inhibiting IL-6 or the IL-6R are currently approved for clinical use; tocilizumab is used in rheumatoid arthritis and systemic sclerosis, whereas siltuximab is approved for treatment of multicentric Castleman’s disease." (PMID 28642760, 2017). "It is also well-defined that IL-6 plays a pivotal role in the bone pathology by its ability to promote the Th17 differentiation observed in rheumatoid arthritis and periodontitis." (PMID 28497028, 2017). "In a similar study, the authors reported the role of histone modifications in elevated IL-6 production in rheumatoid arthritis synovial fibroblasts (RASFs)." (PMID 28262826, 2017). "Tocilizumab, an inhibitory IL-6R antibody, that is approved for rheumatoid arthritis, juvenile idiopathic arthritis, Castleman's disease, and Crohn's disease, inhibits IL-6 signaling." (PMID 28903416, 2017). "Cytokines such as tumour necrosis factor (TNF)-α, interleukin (IL)-1 and IL-6 play a fundamental role in the pathogenesis of rheumatoid arthritis (RA)." (PMID 27913894, 2017). "In the culture model of rheumatoid arthritis, treatment with lunasin reduced cytokine production by IL-6, IL-8, and matrix metalloproteinase-3 and suppressed NF-κB activation in synovial fibroblasts." (PMID 28182687, 2017).
rheumatoid arthritis (continued). "Clinical targeting of the IL-6 pathway is used to treat a number of inflammatory disorders, in particular rheumatoid arthritis." (PMID 28953978, 2017). "The IL-6 signaling pathway is an important therapeutic target for rheumatoid arthritis and Castleman’s disease, and is being investigated in clinical trials for other diseases including systemic lupus erythematosus." (PMID 28334838, 2017). "PLAG caused a decrease in IL-6 production in the RAW264.7 macrophage cell line and in rheumatoid arthritis–fibroblast-like synoviocytes via the regulation of STAT3 signaling without affecting NF-κB signaling." (PMID 29228558, 2017). "Both humanized IL6-specific mAb and IL6Rα-specific mAb, which target IL6 and sIL6Rα respectively, have been shown to be effective in treating rheumatoid arthritis and experimental colitis." (PMID 28645275, 2017). "Recently, we were able to show that pharmacological activation of Nrf2 inhibits NF-κB activity as well as the secretion of the pro-inflammatory cytokines IL-1β and IL-6 in an in vitro model of rheumatoid arthritis." (PMID 28448946, 2017). "As an important inflammatory mediator, IL6 plays an important role in rheumatoid arthritis and osteoarthritis." (PMID 29179499, 2017). "In rheumatoid arthritis, IL-6 stimulates the production of inflammatory cytokines by T and B lymphoid cells, promotes the maturation and differentiation of B cells, and enhances the effects of IL-1β and TNFα." (PMID 28953986, 2017). "Increased IL-6 expression in vivo can lead to several diseases, including rheumatoid arthritis, glomerulonephritis, Crohn’s disease (CD) and Castleman’s disease." (PMID 28358817, 2017). "In rheumatoid arthritis, overproduction of IL-6 is observed and there is a correlation between elevated IL-6 level and clinical indices." (PMID 28289415, 2017). "Low magnesium promotes inflammation and up-regulates IL1α and IL6 production in endothelial cells while magnesium supplementation attenuated the development of OA and rheumatoid arthritis (RA)." (PMID 29115971, 2017). "The reduction of IL-6 has also been observed in a four weeks clinical trial assessing TOFA for rheumatoid arthritis." (PMID 28570653, 2017). "A substantial decrease in methylation at a single CpG site in the promoter of the IL6 gene was measured in patients with rheumatoid arthritis versus healthy controls." (PMID 28545453, 2017). "For example, differential methylation at a single CpG site in the IL6 gene promoter was attributed to differential serum levels of IL6 in patients suffering from rheumatoid arthritis." (PMID 27009155, 2016). "Recently, our group reported that GV1001 decreased the production of TNF-α, IL-1β, and IL-6 in peripheral blood mononuclear cells from rheumatoid arthritis patients through the suppression of p38 MAPK and NF-κB activation." (PMID 27655706, 2016). "DFO treatment on LPS-stimulated microglia prevented the increase of TNF-α, IL-1β, and IL6, and these cytokines have been shown to increase iron uptake in human monocytes from patients with rheumatoid arthritis." (PMID 27733186, 2016). "This prospective, observational cohort included 96 Mexican-Mestizo patients with moderate or severe rheumatoid arthritis (RA), initiating MTX or LEF, genotyped for IL-6 -174G/C polymorphism by PCR-RFLP." (PMID 27738630, 2016). "IL-17A and TNF exert a synergistic effect in FLS in rheumatoid arthritis by increasing the secretion of many factors, including IL-6, IL-8 and granulocyte-colony stimulating factor (G-CSF)." (PMID 27165410, 2016). "Tocilizumab, a humanized antibody that prevents binding of IL-6 to its receptor, is already approved in more than 100 countries worldwide for the treatment of rheumatoid arthritis." (PMID 27493449, 2016). "During inflammation, excess levels of cytokines (IL-1β, IL-6, and TNF-α) lead to the damaging of cells and tissues and the activation of macrophages in inflammation-associated diseases (e.g., rheumatoid arthritis and chronic hepatitis)." (PMID 27493450, 2016).
rheumatoid arthritis (continued). "In contrast to IL-6, whose concentrations can rise up to 100,000 times during inflammation and infection, sIL-6R serum levels increase only slightly, for example, in rheumatoid arthritis patients." (PMID 27493449, 2016). "MEK-162 (Array BioPharma Inc.)is a selective non-ATP-competitive MEK inhibitor initially developed as an anti-rheumatoid arthritis drug due to its profound inhibitory effects on the NF-κB pathway leading to decreased IL-1, IL-6 and TNF activities." (PMID 27708250, 2016). "Neutralizing antibodies and receptor antagonists for blocking IL-6/IL-1 signalling have been developed and approved, for instance, for rheumatoid arthritis and other inflammatory diseases." (PMID 27211851, 2016). "The involvement of IL-6 has been emphasized in certain disorders, and tocilizumab has been demonstrated to be highly efficacious in the treatment of rheumatoid arthritis, systemic juvenile idiopathic arthritis, and Castleman’s disease." (PMID 27068103, 2016). "For example, elevated serum IL-6 levels have been detected in patients with systemic cancers, rheumatoid arthritis, systemic lupus erythematosus, psoriasis and Crohn’s disease as compared to healthy controls or patients with benign diseases." (PMID 27294919, 2016). "The data presented in this article are related to the research article entitled “A critical role of transcription factor YY1 in rheumatoid arthritis by regulation of interleukin-6” (J. Lin, Y. He, J. Chen, Z. Zeng, B. Yang, Q. Ou, 2016)." (PMID 27900357, 2016). "In rheumatoid arthritis, macrophages infiltrate the synovial membrane and produce IL-1, IL-6, TNF-α, and other inflammatory cytokines." (PMID 27609223, 2016). "Previous work showed that IKK expression and NF-κB secretion can increase rheumatoid arthritis synovial fibroblasts apoptosis by improving the level of IL-6 and CD147." (PMID 27420048, 2016). "Although IL‐6R blockade results in upregulation of IL‐6 levels 20, this regimen is feasible also as a long‐time therapy, as recently shown in human rheumatoid arthritis patients." (PMID 26739431, 2016). "Patients with rheumatoid arthritis (RA) have altered circadian rhythm of circulating serum cortisol, melatonin and IL-6, as well as disturbance in the expression of clock genes ARNTL2 and NPAS2." (PMID 26710124, 2015). "Accordingly, MMPs secreted from chondrocytes and activated synoviocytes are involved in cartilage destruction, and MMP-3 and IL-6 are known markers of rheumatoid arthritis and osteoarthritis." (PMID 25884474, 2015). "For example, studies have shown that NF-κB p65 plays a role in constitutive IL-6 production in rheumatoid arthritis synovial fibroblasts." (PMID 26354089, 2015). "TGF-β production has only rarely been associated with suppression mediated by B cells, but therapeutic IL-6 blockade in patients with rheumatoid arthritis leads to an increase in regulatory B cells producing TGF-β." (PMID 25601923, 2015). "Specific targeting of IL-6 using tocilizumab therapy in patients with rheumatoid arthritis led to a significant reduction in circulating Tfh cell numbers and IL-21 production, which was correlated with reduced plasmablast formation." (PMID 25681343, 2015). "It was shown in a clinical study that emotional symptoms are related to the levels of several cytokines, such as IL-6, in several diseases, including rheumatoid arthritis and hemodialysis patients." (PMID 26300773, 2015). "And some groups identified FSTL1 as a new proinflammatory mediator that contributes to rheumatoid arthritis by promoting the expression of TNFα, IL-1β, IL-6 and IL-8, as well as by enhancing the interferon-γ (IFN-γ) signaling pathway in a mouse model." (PMID 25888873, 2015). "The effect of visfatin/Nampt on synovial fibroblasts from patients with rheumatoid arthritis has been extensively studied and is characterized by proinflammatory and prodegradative effects (that is, IL-6, IL-8, MCP-1 and MMP release)." (PMID 24479481, 2014).
rheumatoid arthritis (continued). "The role of constitutive activation of the IL-6-signaling pathway is well established in inflammation, and an increase in IL-6 and soluble IL-6Rα in the synovial fluid of joints in rheumatoid arthritis patients was shown to correlate with disease progression." (PMID 24415766, 2014). "Low dose methotrexate (which partially acts on the IL-6 pathway as demonstrated by reduction of IL-6 plasma levels) has been shown to reduce cardiovascular events in patients with rheumatoid arthritis with hazard ratios between 0.3 and 0.85." (PMID 25484870, 2014). "This is in agreement with the findings by Georganas and co-workers showing that p65 homodimers but not p50 homodimers are important in regulating the expression of both IL-6 and IL-8 in rheumatoid arthritis fibroblast-like synoviocytes." (PMID 25539898, 2014). "Inhibition of this pathway has led to successful treatment of rheumatoid arthritis, but one unforeseen potential complication of anti-IL-6 therapy is bowel perforation." (PMID 25478789, 2014). "It implies that IL-6 is a critical factor in autoimmune diseases, especially in rheumatoid arthritis." (PMID 24729663, 2014). "Aged IL-6 knockout mice show reduced mortality compared to wild type mice after injection with LPS and anti-IL-6 receptor antibodies are good formulation for rheumatoid arthritis." (PMID 24729663, 2014). "Anti-IL-6Rα antibody tocilizumab was the first antagonist of the IL-6-signaling pathway to receive regulatory approval and is currently used for treating rheumatoid arthritis (14, –, 16)." (PMID 24415766, 2014). "Patients with elevated IL-6 show higher mortality and organ failure and anti-IL-6 receptor antibody is supposed to be effective medication for rheumatoid arthritis and Castleman's diseases." (PMID 24729663, 2014). "As hepcidin is regulated by IL-6 available antibodies that already have been approved for rheumatoid arthritis are presently tested for their effect of hepcidin and ACD." (PMID 25646159, 2014). "Several studies have shown that IL-32, an important proinflammatory cytokine in rheumatoid arthritis, enhanced IL-6 and IL-8 production in fibroblast-like synoviocytes." (PMID 25386048, 2014). "Inhibition of IL-6 with the anti-IL-6 antibody clazakizumab was recently shown to be effective at controlling the symptoms of rheumatoid arthritis in a phase IIb clinical study." (PMID 24415766, 2014). "Others have also shown that blockade of IL-6 in patients with rheumatoid arthritis led to enhanced cholesterol and plasma glucose levels, indicating a role for IL-6 in modulation of glucose and lipid metabolism." (PMID 25598708, 2014). "Rheumatoid arthritis (RA) is a chronic disease with joint and systemic inflammation resulting from immunological abnormalities and it has been found that IL-6 plays a key role in the development of this disease." (PMID 24524085, 2014). "Dysregulated IL-6 production plays a role in age-related conditions, such as rheumatoid arthritis, osteoporosis, atherosclerosis, and Alzheimer's disease." (PMID 23641933, 2013). "Dysregulated IL-6 is connected with the pathogenesis of various chronic autoimmune disorders including rheumatoid arthritis (RA), Crohn’s disease and type 1 diabetes, but also cancer." (PMID 24155968, 2013). "Accumulating evidence suggests that IL-6 is closely related to various autoimmune diseases, including rheumatoid arthritis, Crohn’s disease, multiple myeloma and systemic lupus erythematosus." (PMID 23042234, 2013). "IL-6– and IL-1–targeted therapies have been used clinically to treat various diseases, such as rheumatoid arthritis and Castleman’s disease." (PMID 23593346, 2013). "TNF-α is thought to play a crucial role in rheumatoid arthritis since it enhances the production of inflammatory disease-related molecules such as IL-1 or IL-6 in the serum and synovial fluid." (PMID 23762085, 2013).